CXCR4 (C-X-C motif chemokine receptor 4)
Diseases named in the same sentence as CXCR4 in open-access papers (continued):
Sharing a sentence is not in itself a finding about the gene and the disease.
HIV-1 infection (continued). "Therefore, disruption of CXCR4 expression can complement CCR5-specific therapy against HIV-1 infection." (PMID 29141633, 2017). "For example, zinc finger nucleases (ZFN), transcription activator like effector nucleases (TALEN) and clustered regularly interspaced short palindromic repeats (CRISPR)-Cas9 have been utilized to successfully disrupt the HIV-1 co-receptors CCR5 or CXCR4, thereby restricting HIV-1 infection." (PMID 28904745, 2017). "When introduced into primary cells, CD4 T cells expressing C34-conjugated coreceptors exhibited physiologic responses to T cell activation while inhibiting diverse HIV-1 isolates, and cells containing C34-conjugated CXCR4 expanded during HIV-1 infection in vitro and in a humanized mouse model." (PMID 27855210, 2016). "As an alternative mechanism, AAT might directly interact with CD4, CCR5 or CXCR4, or other known HIV-1 infection-related proteins on CD4+ T cells to interfere with the interaction between HIV-1 particles and host cells." (PMID 27473095, 2016). "CXCR4 antagonists were initially developed as new drugs for the treatment of HIV-1 infection." (PMID 27175473, 2016). "To determine whether CXCR4 gene disruption by CRISPR/Cas9 can protect Jurkat T cells from HIV-1 infection, we transduced the Jurkat T cells with the control, #6 or #7 CXCR4-gRNA/Cas9 lentivirus and performed T7EN1 assay." (PMID 26481100, 2015). "CD4+ T cells from older individuals were highly susceptible to CXCR4- and CCR5-tropic HIV-1 infection but produced significantly lower quantities of infectious virus than cells from young individuals because they were highly prone to apoptosis and thus presumably had a very short life span." (PMID 26452480, 2015). "In the setting of HIV-1 infection, downregulation of CXCR4 might translate into a reduction in HIV-1 replication under the influence of μ-opioids, thereby serving a protective function, as suggested in studies performed in macaques." (PMID 25338959, 2014). "Given the observed changes in the level of CXCR4 surface expression following DAMGO treatment and the understanding that co-receptor expression levels correlate with cell susceptibility to HIV-1 infection, the level of impact DAMGO would have on HIV-1 replication was of interest." (PMID 25338959, 2014). "The reduction of HLA-G+ CD4 Treg during progressive HIV-1 infection may be related to their increased susceptibility to HIV-1 infection, which is likely due to enhanced expression of the viral co-receptors CCR5 and CXCR4 demonstrated in this study." (PMID 23382678, 2013). "Moreover, it has been suggested that a high CXCR4 density on the surface of CD4+ T cells during the course of HIV-1 infection favors the emergence of X4 virus isolates." (PMID 23844079, 2013). "In the case of HIV-1 infection, CXCR4 has been defined as a co-receptor which, binding by the virus, mediates membrane fusion and signalling transduction that might facilitate viral infection and pathogenesis." (PMID 24015922, 2013). "However, once HIV-1 infection is established, it is able to choose CXCR4 as an alternative co-receptor." (PMID 24284874, 2013). "Primary HIV-1 infection targets CCR5+ immune cells, as the disease progresses, alternate co-receptors such as CXCR4 may become predominant due to the loss of the accessible CCR5+ in the cellular pool." (PMID 24146801, 2013). "Despite intense study, the importance of GPCR-mediated signaling during CXCR4-tropic HIV-1 infection remains unclear." (PMID 22448282, 2012). "Therefore, CB2 activation reduces CXCR4-tropic HIV-1 infection in primary CD4+ T cells in a dose-dependent and receptor-specific fashion." (PMID 22448282, 2012). "Furthermore, CXCR4 not only acts as co-receptor for CXCR4-using HIV-1 infection but is also involved in the regulation of T-cell migration, proliferation and differentiation." (PMID 22412885, 2012).
HIV-1 infection (continued). "Interestingly, HD5 was significantly more efficient than HNP1 in downmodulating CXCR4 in activated primary T cells, which are the principal target of HIV-1 infection." (PMID 23028850, 2012). "Also, Tat upregulates the expression of specific chemokine receptors, such as CCR5 and CXCR4, which are important for HIV-1 infection." (PMID 22471703, 2012). "Thus, the interaction of the A120 mAb with CXCR4 inhibits not only X4, but also R5 HIV-1 infection of in vitro activated PBMCs, via mechanisms detailed herein." (PMID 22018245, 2011). "Furthermore, as a result of differentiation, expression of other common cellular ligands essential for HIV-1 infection, such as CXCR4, CCR4, and CCR5, distinctly increased." (PMID 21226936, 2011). "Finally, we believe that our data have implications in the pathogenesis of CCR5-tropic compared to CXCR4-tropic HIV-1 infection in the thymus." (PMID 21904619, 2011). "Furthermore, sustained CD28 signaling, as well as IL-4, can upregulate the expression of CXCR4 and, consequently, favor X4 HIV-1 infection and replication in activated T cells." (PMID 21284907, 2011). "A greater understanding of CXCL12/CXCR4 signaling pathways may lead to more selective therapeutics for diseases such as cancer and HIV-1 infection." (PMID 21949786, 2011). "Similarly gp120 interaction with cell chemokine receptor CCRS5 and CXCR4 are the key events for HIV-1 infection." (PMID 21108852, 2010). "Therefore, studying the effects of HIV-1 Gag expression on CXCR4 downregulation kinetics in these cells should provide insight into the physiologic processes occurring during HIV-1 infection." (PMID 18267010, 2008). "CXCR4 was concentrated in intracellular compartments in RH9 cells after HIV-1 infection." (PMID 18190699, 2008). "Thus, these two coreceptors, CCR5 and CXCR4, have been thought to play major roles in HIV-1 infection and the development of related disorders." (PMID 18577234, 2008). "Jurkat cells express endogenous CXCR4, and are authentic targets of HIV-1 infection in vivo." (PMID 18267010, 2008). "CXCR4 appears to be concentrated in intracellular compartments in H9 cells after HIV-1 infection." (PMID 18190699, 2008). "CXCR4 was concentrated in intracellular compartments in H9 cells after HIV-1 infection." (PMID 18190699, 2008). "Mutants of SDF-1 might be used as inhibitors of CXCR4 to inhibit HIV-1 infection." (PMID 31540474, 2019). "We then tested whether the expression of CXCR4 (P191A) protected cells from HIV-1 infection." (PMID 29872154, 2018). "Besides CCR5, CXCR4 is a main co-receptor for HIV-1 infection." (PMID 30233568, 2018). "Therefore, this approach could provide a new strategy for CXCR4-targeted therapy against HIV-1 infection." (PMID 29872154, 2018). "In addition, TGFβ may increase the expression of CCR5 and CXCR4, thereby increasing the susceptibility of CD4+ T cells to HIV-1 infection." (PMID 25802474, 2015). "Finally, we assessed whether the expression of other co-receptors, CXCR6, CCR5 and CXCR4, also was modulated in the context of HIV-1 infection." (PMID 24558379, 2014). "Therefore, the clinical use of CB2R agonists in the treatment of AIDS symptoms may also exert beneficial adjunctive antiviral effects against CXCR4-tropic viruses in late stages of HIV-1 infection." (PMID 22448282, 2012). "It has been hypothesized that the absence of CXCR4-using variants early in HIV-1 infection may be due to their higher vulnerability to the host adaptive immune responses, in particular neutralizing antibodies." (PMID 21284904, 2011). "CXCL12 and CXCR4 knockout mice are embryonic lethal and signaling through the CXCL12/CXCR4 axis has been implicated in organogenesis, autoimmunity, WHIM syndrome (Warts, Hypogammaglobulinemia, Infections, and Myelokathexis), and human immunodeficiency virus -1 (HIV-1) infection." (PMID 21949786, 2011). "In addition, CXCR4 is a functional co-receptor for HIV-1 infection of human macrophages." (PMID 16740160, 2006).
HIV-1 infection (continued). "HIV-1 uses CXCR4 or CCR5 as coreceptors for entry into target cells, and ligands binding to these receptors inhibit HIV-1 infection." (PMID 40394646, 2025). "As expected, CXCL12 and AMD3100 specifically inhibited CXCR4-tropic HIV-1 infection, with IC50 values of 47.9 ± 8 nM and 5.3 ± 0.4 nM, respectively, while Maraviroc blocked CCR5-tropic HIV-1 infection." (PMID 40394646, 2025). "The authors concluded that the mechanism by which THC suppresses HIV-1 infection includes a reduction in HIV receptor (CD4, CCR5, and CXCR4) expression on the cell surface, which diminishes entry efficiency." (PMID 40141240, 2025). "Chemokine receptors CXCR4 and CCR5 have been extensively studied due to their roles in leukocyte development and inflammation and their status as coreceptors for HIV-1 infection, among other roles." (PMID 37690681, 2023). "The chemokine receptor CXCR4 and its ligand CXCL12 regulate leukocyte trafficking, homeostasis and functions and are potential therapeutic targets in many diseases such as HIV-1 infection and cancers." (PMID 36770826, 2023). "During HIV-1 infection, a proportion of CD4+ TSCM exhibit increased sensitivity to HIV-1 infection by expressing the HIV core receptors CCR5 and CXCR4." (PMID 36891319, 2023). "HIV-1 infection is mediated by a viral envelope subsequently binding to CD4 receptor and two main coreceptors, CCR5 (R5) for primary infection and CXCR4 (X4) in chronic infection." (PMID 36647730, 2023). "Initial steps of HIV-1 infection involve the interactions of HIV-1 envelope protein gp120 with CD4 and CXCR4 and/or CCR5 on host cells, rendering such interactions promising targets for blocking HIV-1 entry." (PMID 38131305, 2023). "Canonical HIV-1 infection uses both the main HIV-1 receptor, CD4, and the co-receptors, primarily CXCR4 and CCR5." (PMID 37209263, 2023). "In human CD4+ T cells, GPI-10E8 and its bifunctional derivatives blocked both CCR5- and CXCR4-tropic HIV-1 isolates efficiently, and the modified cells displayed robust survival selection under HIV-1 infection." (PMID 34821542, 2022). "Selected sgRNA efficiently induced editing of the CXCR4 gene in human CD4+ cell lines and made these cell lines resistant to HIV-1 infection." (PMID 35628210, 2022). "In this study, CCR5 and CXCR4 were both overexpressed on platelet-CD4+ T cell aggregates compared to their counterparts and were upregulated during HIV-1 infection, indicating that these cells were more permissive to R5 and X4 HIV-1 strains." (PMID 34987521, 2021). "More importantly, GPI-m36.4-modified human CD4+ cells (CEMss-CCR5) were exceptionally resistant to both CCR5- and CXCR4-tropic HIV-1 isolates and had a robust selective survival advantage over unmodified cells following HIV-1 infection." (PMID 33462383, 2021). "Only recently, dendritic simplification and cognitive flexibility in a transgenic rat model of HIV-1 infection was rescued by CXCL12, an endogenous chemokine and antagonistic ligand for the CXCR4 receptor, presumably outcompeting gp120 interaction with CXCR4." (PMID 33705493, 2021). "At the time of primary HIV-1 infection (PHI), the viruses that can use CXCR4, exclusively (X4-tropic) or in addition to CCR5 (R5X4- or dual-tropic), are rare (< 10%), but their proportion increases as infection progresses." (PMID 33872329, 2021). "During the progression of HIV-1 infection, M-tropic HIV-1 that uses the CCR5 co-receptor undergoes a change in co-receptor use to CXCR4 that is predominately T-cell-tropic." (PMID 32971935, 2020). "In contrast to the popularity of the topics of CXCR4 as an HIV-1 coreceptor and SDF-1 as an inhibitor of HIV-1 infection, relatively few articles have addressed the intrinsic functions of SDF-1 and CXCR4 in the pathogenesis of HIV-1 infection and AIDS." (PMID 32154191, 2020). "During the progression of HIV-1 infection, macrophage tropic HIV-1 that use the CCR5 co-receptor undergoes a change in co-receptor use to CXCR4 that is predominately T cell tropic." (PMID 32971935, 2020).
HIV-1 infection (continued). "CXCR4 has long been a classic representative of GPCR family and plays crucial roles in HIV-1 infection and cellular metastasis, making it a target of intense medicinal interest." (PMID 31412600, 2019). "It is thought that the different HPgV-1 genotypes have different tropisms to the CXCR4 and CCR5 coreceptors used by HIV-1 for entry into host cells, which would be determinant in the evolution of HIV-1 infection." (PMID 31309117, 2019). "It is reported that in the early stage of HIV-1 infection, the co-receptor of HIV-1 is CCR5, which is then gradually converted into CCR5/CXCR4, and finally, further converted to CXCR4." (PMID 31480738, 2019). "In this review, we examine studies that have utilized different gene editing technologies to edit CCR5 or CXCR4 and discuss how different mechanisms of HIV-1 infection can be inhibited by editing the co-receptors needed for HIV-1 infection." (PMID 30619107, 2018). "By combining a CRISPR-Cas9 strategy and piggyBac transposon system, we achieved efficient replacement of wild-type CXCR4 with a CXCR4 P191A homozygous mutant in an HIV-1 reporter cell line and observed significant inhibition of HIV-1 infection." (PMID 29872154, 2018). "Melittin is effective in inhibiting HIV type 1 (HIV-1) infection, with a 50% inhibitory concentration (IC50) of 2.4 μM for CXCR4-tropic viral strains and 3.6 μM for CCR5-tropic viral strains." (PMID 30034176, 2018). "Inclusion of increasing concentrations of CXCL12 seemed to diminish the enhancement of X4 HIV-1 infection by CXCL14, which is in agreement with the critical role played by CXCR4 in this process." (PMID 28360196, 2017). "We also showed that CXCR4-edited primary CD4+ T cells proliferated normally and were resistant to HIV-1 infection." (PMID 29141633, 2017). "Our results suggest that simultaneous genome editing of CXCR4 and CCR5 by CRISPR-Cas9 can potentially provide an effective and safe strategy towards a functional cure for HIV-1 infection." (PMID 28904745, 2017). "The results indicated that both lenti-X4R5-Cas9-#1 and lenti-X4R5-Cas9-#2 mediated CXCR4 and CCR5 knockout conferred TZM-bl cells resistant to X4- or R5-tropic HIV-1 infections." (PMID 28904745, 2017). "HIV-1 infection of CD4+ T cells involves binding of the viral protein gp120 to the primary cellular receptor CD4 and either of the co-receptors, CCR5 or CXCR4." (PMID 28904745, 2017). "In most cases of HIV-1 infection, although HIV-1 uses CCR5 to mediate entry to cells, CXCR4 can function as a co-receptor at the late stages of infection, which contributes to disease progression." (PMID 28904745, 2017). "Key players in HIV-1 infection, CCR5 and CXCR4 GPCRs function as co-receptors for virus entry into CD4+ target cells." (PMID 26629902, 2015). "For HIV-1 infection, CD4/CXCR4/CCR5+ TZM β-galactosidase reporter target cells were exposed to wild-type or drug-resistant HIV-1 variants (1 ng of p24) together with increasing concentrations of DMSO or CypI—CsA, ALV, or CPI-431-32." (PMID 26263487, 2015). "We examined expression of CD4, CXCR4, and CCR5, receptors for HIV-1 infection, in CD14-derived osteoclasts and macrophages." (PMID 25809599, 2015). "The third variable region (V3 loop) of the HIV-1 envelope protein (gp120) plays an important role in HIV-1 infection, being the primary determinant for binding to one of the two 7-transmembrane receptors CCR5 (R5-tropic) and CXCR4 (X4-tropic)." (PMID 25785610, 2015). "In the context of HIV-1 infection, two GPCRs are important, i.e., the chemokine coreceptors CCR5 and CXCR4." (PMID 26835447, 2015). "During HIV-1 infection, because of the extensive virus evolution, coreceptor usage preference change from CCR5 to CXCR4 emerges in more than 50% of the infected individuals over time and is associated with progression to AIDS." (PMID 24465884, 2014).
HIV-1 infection (continued). "Sexual transmission is the main route of HIV-1 infection and the CCR5-using (R5) HIV-1 is predominantly transmitted, even though CXCR4-using (X4) HIV-1 is often abundant in chronic HIV-1 patients." (PMID 24990163, 2014). "Our system facilitates the quantitation of HIV-1 infection in alternative T cell subsets by CCR5- and CXCR4-using viruses across different HIV-1 subtypes, and will be useful for studies of HIV-1 pathogenesis and viral reservoirs." (PMID 24517971, 2014). "Overexpression of gelsolin-EGFP did not affect the cellular distribution or the cell-surface expression of CD4, CXCR4 or CCR5, the receptors required for HIV-1 infection (respectively)." (PMID 23575248, 2013). "In order to investigate the potential role of suPAR forms in HIV-1 infection of secondary lymphoid organs, tonsil histocultures were established from HIV-1 seronegative individuals and infected ex vivo with CCR5- and CXCR4-dependent HIV-1 strains." (PMID 23923008, 2013). "As the goal was to eventually investigate the role of IL-27 in DCs with regard to HIV-1 infection, IL-27 treated DCs were also profiled and found to have similar levels of CD4, CCR5 and CXCR4 as iDCs or mDCs." (PMID 23527130, 2013). "CXCR4- and CCR5- tropic HIV-1 infection was effectively inhibited in hu-BLT mouse spleen-derived human CD4+ T-cells ex vivo." (PMID 23300932, 2012). "Given a previous report, which indicated that CXCR4 signaling enhances HIV-1 infection in resting cells, we chose to investigate the functional consequence of CB2R stimulation on CXCR4-mediated signaling." (PMID 22448282, 2012). "HCV was originally thought to be strictly hepatotropic, while the main cell targets for HIV-1 infection are mononuclear leukocytes bearing CD4 and the chemokine receptors C-C chemokine receptor type 5 (CCR5) and chemokine (C-X-C motif) receptor 4 (CXCR4)." (PMID 22471703, 2012). "Lesions or microtrauma would also render the outer foreskin and/or shaft of the penis vulnerable to HIV-1 infection, providing access to an abundance of cells expressing CD4, as well as CCR5 and CXCR4." (PMID 21284905, 2011). "The data described herein have identified a unique epitope of CXCR4 whose ligation not only directly inhibits X4 HIV-1, but also indirectly inhibits R5 HIV-1 infection by inducing higher levels of natural CCR5 ligands." (PMID 22018245, 2011). "HIV-1 infection begins with HIV-1 envelope gp120 binding to CD4 and chemokine co-receptors CCR5 (for M-tropic strains) or CXCR4 (for T-tropic strains) on the cell surface of HIV-1 target cells." (PMID 19656383, 2009). "We here report high-level production in E.coli of 4 human GPCRs, namely chemokine receptors (hCRs) CCR5, CCR3, CXCR4 and CX3CR1 that are directly involved in HIV-1 infection, asthma and cancer metastasis." (PMID 19223978, 2009). "Previously, we demonstrated that during HIV-1 infection of resting CD4 T cells, the viral envelope-CXCR4 signaling activates cofilin to overcome the static cortical actin restriction." (PMID 18928553, 2008). "During progression of stages in HIV-1 infection, HIV-1 strains that use CXCR4 as a coreceptor (X4 strains), especially subtype B strains, have been detected." (PMID 18577234, 2008). "These compounds inhibit HIV-1 infection of T cells by blocking the co-receptors CCR5 and CXCR4, respectively." (PMID 16916447, 2006). "During wild-type HIV-1 infection, CD4 and the coreceptors CXCR4 and CCR5 are excluded from the HIV-1 envelope through interactions with HIV-1 Nef protein." (PMID 16371160, 2005). "AMD3100 (Plerixafor) is a selective CXCR4 chemokine receptor antagonist that blocks the interaction between CXCR4 and its natural ligand CXCL12, a critical axis involved in various pathological conditions, including HIV-1 infection, tumor progression, and metastasis." (PMID 40698080, 2025).